IL6 (interleukin 6)
Diseases named in the same sentence as IL6 in open-access papers (continued):
Sharing a sentence is not in itself a finding about the gene and the disease.
COVID-19 (continued). "However, other investigators noted modestly elevated IL-6 concentrations with high rates of thrombosis and markedly elevated D-dimer concentrations, which suggested that COVID-19 involved hypo-inflammatory vasculopathy rather than an inflammatory cytokine storm." (PMID 34214123, 2021). "Thus, IL-6 should not be ignored in the treatment of severe COVID-19." (PMID 33628091, 2021). "Furthermore, cytokines, especially interleukin-6, were not routinely measured, which may be better predictors, especially regarding the so-called ‚COVID-19 cytokine storm ‘, to elucidate COVID-19 positive from negative patients." (PMID 33931692, 2021). "However, although certain studies have shown that plasma IL-6 and IL-10 could be used as factors to predict the progression of COVID-19, in our cohort, their values could not be used in isolation to distinguish between patient groups." (PMID 34960790, 2021). "Compared to both healthy controls and patients with viral or bacterial pneumonia, COVID-19 patients, especially severe cases, have in their peripheral blood reduced numbers of CD14+CD16-DR+ “classical” monocytes, which may be due to the increased levels of IL-6 and/or dysregulated myelopoiesis." (PMID 33481950, 2021). "Furthermore, the activation of EGCs is attended by a vast release of IL-6 and other inflammatory intermediates that could result in acute respiratory discomfort, as observed in the SARS-CoV-2 induced cytokine storms experienced by COVID-19 patients." (PMID 34768321, 2021). "Furthermore, we have demonstrated in vitro efficacy of NIC-hLYS reducing complications related to COVID-19, most notably secondary bacterial pneumonia by MRSA and dampening (but not complete suppression) of TNF-α and IL-6, which are known markers for COVID-19 disease severity." (PMID 33571320, 2021). "Moreover, clusters #3 and #4 correlated significantly with the level of oxygen supplementation, IL-6, and length of stay in a tertiary hospital, all indicators of disease severity, which further suggests a link between CD16+ LDG subsets and increased disease severity in acute COVID-19." (PMID 34228753, 2021). "Notably, IP-10, together with IL-6 and IL-10, is reported to constitute a severity-related triad that anticipates subsequent clinical progression (specifically) in COVID-19 patients, but not in non-COVID-19 patients with lower respiratory tract infections." (PMID 33673459, 2021). "Furthermore, other authors suggested that plasma sTREM-1 concentrations are related to COVID-19 severity and can discriminate between survivors and non-survivors, and sTREM-1 and IL-6 concentrations can be used as screening tools to decide treatment in patients with COVID-19." (PMID 34960790, 2021). "However, a few references also relate it to COVID-19, in particular, bioinformatics predictions indicate that miR-138-5p may target SARS-CoV-2 genes as well as IL6 and IL-8 cytokines, two major actors in the COVID-19-induced “cytokine storm” associated with poor outcomes." (PMID 34198800, 2021). "Of note, non-response to IL-1 and IL-6 blocking therapies has been commonly attributed to late administration of these agents at advanced disease stage but the optimal timing of anti-inflammatory treatment initiation in COVID-19 has never been clearly established." (PMID 33995419, 2021). "Similarly, IFN-α2b treatment of COVID-19 patients as a single agent or in combination with arbidol significantly reduced the duration of SARS-CoV-2 in the upper respiratory tract and reduced the duration of IL-6 and C-Reactive Protein (CRP) inflammatory markers in the blood." (PMID 32882823, 2020). "We believe that targeting the central pathway (IL-1β, TNF-α, IL-6), balancing the Th1 and Th2 response, and administering long-term anti-inflammatory therapy might be promising prospects to reduce cardiovascular impairment and even MODS during the acute and recovery phases of COVID-19." (PMID 32426374, 2020).
COVID-19 (continued). "Also, some test results, such as chest CT, IL-6, and pro-calcitonin, known as prognostic factors for COVID-19, could not be included in the analysis because of missing data." (PMID 33291617, 2020). "Levels of IL-6, leptin and adiponectin were determined at baseline and compared between groups, in order to test the hypothesis that proinflammatory adipokines are higher in patients with COVID-19 with MetS compared with those without MetS." (PMID 33328246, 2020). "Since EBV can induce immune dysregulation and expression of IL-6 in peripheral blood mononuclear cells (PBMCs) via deoxyuridine triphosphate nucleotidohydrolase (dUTPase) in vitro, one might speculate that EBV acts as an additional inflammatory trigger in critically ill COVID-19 patients." (PMID 33228750, 2020). "Pro-inflammatory cytokines and anti-inflammatory cytokines in serum, including IL-2R, IL-6, TNF-α, and IL-10, were significantly higher in most severe patients than in moderate patients, suggesting that cytokine storms may be related to the severity of COVID-19." (PMID 33232275, 2020). "Interestingly, plasma IL-6 levels were either not different, or only slightly different in the early phase of disease progression between mild and severe/critically ill COVID-19 patients." (PMID 32766256, 2020). "Second, due to the retrospective design and the urgency of the epidemics, anthropometrics data is lacking and factors such as levels of interleukin-6 and ferritin were not measured, so their role in predicting COVID-19 severity could not be considered during data analyses." (PMID 33521032, 2020). "Taken together, our findings may assist future management of COVID-19 patients, as they may exhibit diverse expression profiles of molecular regulators such as DANCR and NEAT1, in conjunction with previously depicted inflammatory mediators such as IL-1, IL-6, TNF, and more." (PMID 33163005, 2020). "After univariate and multivariate logistic regression, the levels of hs-CRP, IL-6, and TNF-α were shown to be positively correlated with the incidence of myocardial injury, supporting the hypothesis that a high systemic inflammatory burden might contribute to myocardial injury in COVID-19 patients." (PMID 32733921, 2020). "Moreover, given the recent evidence in different hospitals suggesting IL-6 and TNF-α inhibitor drugs as a possible therapy for COVID-19, we aimed to highlight that a dietary intervention could be useful to prevent the infection and/or to ameliorate the outcomes during therapy." (PMID 32354030, 2020). "Furthermore, serum concentrations of IL-10, IL-6, and TNF-α were significantly lower in patients in the disease resolution in comparison to the disease period, whereas the total number of T cells, CD4+ T cells, and CD8+ T cells was restored during the decline period of COVID-19." (PMID 32916812, 2020). "Additionally, several lines of evidence indicated that asiaticoside (a saponin), borneol (a terpene), catalpol (an iridoid) as other phytochemicals declined the neuronal levels of TNF-α, IL-6, TLR4, NF-κB, IL-β and IL-8, thus may be hopeful agents against neurological symptoms in COVID-19." (PMID 33708124, 2020). "Studies have shown that elevated serum levels of inflammatory cytokines such as IL-6 and TNF-α at the time of hospitalization are strong negative prognostic markers in COVID-19 patients." (PMID 40677723, 2025). "Clinical outcome was generally in positive correlation with IL-6 and LDH, while in negative correlation with Ct values of RT-qPCR testing and application and quantity of vaccines in COVID-19 male patients." (PMID 40868247, 2025). "Severe SARS-CoV-2 infection induces aberrant innate immune activation with elevated IL-6, IL-1β, TNF-α, and other soluble mediators; this hyperinflammatory state is a potent nonspecific mechanism of multi-organ injury in severe COVID-19." (PMID 41462971, 2025).
COVID-19 (continued). "Our findings suggest that all severe COVID-19 patients, regardless of existing immunosuppression or cancer diagnoses, experience CD8 + T cell depletion, higher IL-6 concentrations, and importantly, delayed type I IFN peaks." (PMID 40489562, 2025). "Our results show a decrease in LTA with increased IL-6, suggesting that LTA is not the driver of elevated levels of IL-6 production in COVID-19." (PMID 40687705, 2025). "Specifically, we compared the levels of IFN-γ, IL-6, IL-22, IL-4, IL-8, IL-10, and IL-17A between anti-SARS-CoV-2 IgG-positive and seronegative individuals, all without a history of COVID-19." (PMID 40160814, 2025). "After adjusting by group and sensitivity analysis, they observed higher IL-6 levels (SMD: 0.30, 95%CI: 0.12–0.49) in patients with post-COVID-19 condition when compared with those without." (PMID 41516235, 2025). "SARS-CoV-2 infection triggers inflammation in the microvascular endothelial cells in multiple organs, including the heart as markers of endothelial inflammation - IL-6, TNF-α, IL-1β, IL-15 – were increased in the lungs of COVID-19 non-survivors." (PMID 41415584, 2025). "In the COVID-19 cohort, correlations of LPC species with CRP, procalcitonin, and IL-6 were not significant (p > 0.05 for all)." (PMID 41007672, 2025). "In contrast, COVID-19 negative individuals showed lower-magnitude responses for TNF, IL-10, and IL-17A but exhibited multiple peaks in IL-2, IL-6, and IFN-γ production." (PMID 40406109, 2025). "Our objective was to compare the kinetics of three conventional markers routinely used in everyday practice (CRP, PCT, and IL-6) and two non-conventional markers (NLR and PLR) in critically ill COVID-19 patients requiring life-maintaining therapy." (PMID 39336857, 2024). "Omicron-infected COVID-19 patients exhibited significantly elevated systemic inflammatory markers, including CRP, IL-6, LDH, and ferritin, which showed negative correlations with SOD activity." (PMID 38464514, 2024). "In this study, we performed a systematic review and meta-analysis to compare IL-6, ferritin and LDH in VTE and non-VTE COVID-19 patients in order to shed light on the prevention and treatment of VTE." (PMID 38493138, 2024). "In the present study, higher levels of STING and cGAS gene expression and plasma levels of IFN-α, IL-6, and TNF-α were identified in patients with the severe form of acute COVID-19 than in patients with the nonsevere form." (PMID 38424312, 2024). "Collectively, our study revealed that COVID-19-affected T2DM patients exhibited higher levels of several inflammatory mediators, including CRP, IL-6, and TNF-α in comparison to COVID-19 non-DM patients." (PMID 38675414, 2024). "Furthermore, among individuals admitted to an intensive care unit (ICU) for COVID-19, serum S100B levels were elevated in non-survivors compared to survivors, showing a notable correlation with inflammatory markers, such as lymphocyte counts and interleukin-6 (IL-6) levels." (PMID 39451987, 2024). "The time from the onset of COVID-19 symptoms to clinical cure ranges from 8 to 53 days, with large inter-individual variability, and IGFBP-2, CRP, procalcitonin, and IL-6 were not related to the time of blood collection in our cohort." (PMID 38255230, 2024). "Similar to IL-6, IL-10, and TNF- α, CCL-3 and CXCL-13 levels were not significantly different between mild-to-moderate COVID-19 patients, recovered individuals, and healthy controls." (PMID 38646483, 2024). "Independent samples t-test was used to compare the anti-SARS-CoV-2 IgG, IL-6, and CRP levels between the participants with and without post-COVID-19 symptoms." (PMID 39056056, 2024). "Individuals with COVID-19 and type 2 diabetes were reported to have significantly greater levels of TH1 cytokines such as IFN-γ, and IL-6 compared with individuals with COVID-19, but not diabetes." (PMID 37934800, 2024).
COVID-19 (continued). "In the analysis of plasma cytokine levels, it was observed that patients with the severe form of COVID-19 had higher levels of IFN-α (p = 0.0006), TNF-α (p = 0.0137) and IL-6 (p = 0.0071) than those with the nonsevere form." (PMID 38424312, 2024). "The serum IL-6, IL-1β, and TNF-α expression levels were measured by RT-PCR in COVID-19 patients (n = 41), stratified into non-survivors (n = 23) and survivors (n = 18), and in the serum of subjects in the control group (n = 20)." (PMID 39201618, 2024). "Higher concentrations of IL-2, IL-6, IL-8, and TNF-α were also reported in ICU patients with COVID-19 in comparison to non-ICU patients." (PMID 38707035, 2024). "This study found that the levels of cytokines IL-6, IL-8, IL-10, sCD25, and chemokines IP-10, and MIG in the peripheral blood of severe COVID-19 patients were significantly higher than those in non-severe patients (P < 0.05)." (PMID 39654886, 2024). "This is consistent with findings in COVID-19 patients, in which NSAID treatment suppressed neutralizing cytokines and immune responses such as IL-6, MIP-1, and GM-CSF without affecting the infiltration of innate and adaptive immune cells into the lung." (PMID 39281680, 2024). "Statistical analysis revealed that levels of cytokines IL-6, IL-8, IL-10, sCD25, and chemokines IP-10, and MIG in the peripheral blood of severe COVID-19 patients were significantly higher than those in non-severe patients (P < 0.05)." (PMID 39654886, 2024). "A similar approach to subtyping patients with COVID-19 ARDS early in the pandemic revealed significant overlap with non-COVID ARDS subtypes, but with the exception of IL-6, data on biomarkers of lung injury and inflammation were unavailable." (PMID 38383504, 2024). "We identified higher levels of D-dimer, IL-6, IL-8, IL-13, Angpt-2, Pentraxin-3, S100B, MMP-8, and u-PAR in the plasma of critical COVID-19 non-survivors than in that of survivors." (PMID 39507250, 2024). "Similar to IFN-ɣ and IL-6 mRNA expression, TNF-α mRNA expression was significantly higher in the nasopharynx of COVID-19 patients than in non-infected subjects." (PMID 39339947, 2024). "Plasma PCSK9 levels of the COVID-19 patients did not correlate with C-reactive protein (CRP), procalcitonin, IL-6, ferritin, or leukocyte count, illustrating that, at least in SARS-CoV-2 infection, higher PCSK9 is not simply a marker of inflammation." (PMID 39051245, 2024). "In univariable analyses, individuals with PASC tended to have lower levels of sCD14, IL10, IL17, IL1β, IL6 and TNFα compared to participants without PASC at 9–12 weeks after COVID-19 onset." (PMID 39008486, 2024). "Higher levels of D-dimer (p = 0.0306), NT-proBNP, IL-6, homocysteine, and TNF-α appeared in COVID-19 DM patients than in non-DM COVID-19 subjects, and these were found to be statistically significant (p < 0.0001)." (PMID 38675414, 2024). "The lack of benefit of DMF is in contrast to IL-6 and JAK inhibitors, which reduce COVID-19 mortality when used in addition to corticosteroids." (PMID 38296965, 2024). "Our findings indicate a non-significant tendency for higher levels of IL-6 in both the DENV/COVID-19 infected and COVID-19-only groups than in the donor group." (PMID 39583156, 2024). "In contrast, in COVID-19 patients, ACBP plasma concentrations correlated with the neutrophil/lymphocyte ratio, CRP and IL-6 but not IL-1β and IL-8." (PMID 39835130, 2024). "Some pro-inflammatory cytokines and chemokines, such as IL-6, IL-1, IL-18, and TNF-α, have been detected in high levels in patients with severe COVID-19 compared to non-severe cases." (PMID 39504070, 2024). "In a retrospective study, LMW heparin was shown selectively to reduce plasma IL-6 concentrations, but not concentrations of IL-2, TNF-α, IL-4, IL-10 or IFN-γ in patients with COVID-19." (PMID 37111341, 2023).
COVID-19 (continued). "Hospitalized COVID-19 patients who suffered barotrauma had higher inflammatory biomarkers including IL-6, LDH and D-dimer than admitted COVID-19 patients without barotrauma." (PMID 37400813, 2023). "Correspondingly, circulating levels of pro-inflammatory cytokines IL-6, TNF and IFN-γ, and of anti-inflammatory IL-10, were altered with respect to reference values but similar in COVID-19 and No COVID-19 patients." (PMID 37408073, 2023). "We found increased levels of IL-1ra, IL-6, IL-8, IL-13, TNF-α, IP-10, MCP-1, MIP-1α, and G-CSF in both, COVID-19 negative and COVID-19 positive sepsis patients, as compared to healthy controls." (PMID 36980378, 2023). "Still, according to a Chinese study, MAFLD subjects have significantly higher circulating IL-6 levels than non-MAFLD, and there is a significant interaction between elevated IL-6 levels with severe COVID-19 in MAFLD." (PMID 37445349, 2023). "In this study, the IL-6 level and NLR were not normally distributed (Kolmogorov–Smirnov); thus, the differences in IL-6 levels and NLR in the two COVID-19 groups were analysed using the Mann–Whitney test." (PMID 38099004, 2023). "The findings indicated that the patients with severe symptoms had significantly higher levels of procalcitonin (PCT), interleukin-6 (IL-6), ESR, and CRP than that of the nonsevere cases of COVID-19." (PMID 37168698, 2023). "IL-6, LDH, CRP and PCT levels were significantly higher in non-survivor hospitalized patients affected by COVID-19, representing not only markers of inflammation but also in-hospital mortality." (PMID 36836679, 2023). "While there is an association of CRP with severity in our cohort (severe vs. moderate COVID-19: 14.83 mg/dl vs. 7.53 mg/dl, p = 0.05), we did not observe a correlation between PP aggregates and the inflammatory markers CRP and Interleukin-6." (PMID 37935793, 2023). "The strength of our study lies in the comprehensive dynamics of the pro-inflammatory (mainly IL-1β, IL-6, IL-8, TNF-α) and anti-inflammatory (IL-10) cytokines over time and their comparison with non-severe COVID-19 cases as supporting evidence." (PMID 37384050, 2023). "In the COVID-19 patients, those that had AKI had significantly higher IL-6 levels compared to those that had no AKI (20.4 vs. 5.53 pg/mL)." (PMID 36983566, 2023). "In the subcohort of COVID-19 patients plasma chemerin did not correlate with CRP (r = 0.219, p = 0.339), procalcitonin (r = 0.112, p = 0.630) or IL-6 (r = 0.165, p = 0.475)." (PMID 37509420, 2023). "While the levels of cytokines in lung in COVID-19 patients have not been analyzed, the plasma levels of IL-6, TNF-α, and IL-10 were highly increased in severe COVID-19 patients with comparable levels to non-COVID-19 patients." (PMID 37724101, 2023). "A positive correlation of METRNβ with IL10, IL6, and CCL7 was observed among the COVID-19 patients, while a negative correlation was observed with sCD40L." (PMID 36798115, 2023). "In light of the results of this study, the time from symptoms’ onset to reporting to the medical facility does not influence the prognostic value of CRP, IL-6, and NLR in initially non-severe COVID-19 patients." (PMID 36831898, 2023). "Plasma Gal-9 shows positive correlations with proinflammatory mediators, especially IL-6, IP-10, and CRP, and a negative correlation with an anti-inflammatory cytokine, transforming growth factor-β (TGF-β), in COVID-19 patients." (PMID 36835000, 2023). "The levels of IL-6 (p= 0.0300) and TNF-α (p = 0.0800) were higher in patients with severe COVID-19 than in those with the non-severe form." (PMID 37138871, 2023). "Accordingly, anti-cytokine aAbs (e.g., antibodies against IFN-α, IFN-ε, IL-6, IL-22, GM-CSF, and TNF-α) were proposed for COVID-19 and non-COVID-19 treatment, although with different results, since some improved clinical outcomes, while others had no benefit." (PMID 37243300, 2023).